ZNF209P (zinc finger protein 209, pseudogene)
Synonyms: formerly ZNF209
Gene: Unprocessed pseudogene on chromosome 19 (22,463,922 to 22,473,036, forward strand). Ensembl gene ENSG00000269138.
Diseases named in the same sentence as ZNF209P in open-access papers:
ZNF209P is named in the same sentence as 1 disease in open-access papers, as found by Europe PMC text mining. Sharing a sentence is not in itself a finding about the gene and the disease.
ZNF209P shares sentences with these, for which no sentence is quoted: ischemic stroke (1 paper).